RN7SL465P (RNA, 7SL, cytoplasmic 465, pseudogene)
Gene: Miscellaneous RNA gene on chromosome 6 (38,744,086 to 38,744,386, forward strand). Ensembl gene ENSG00000244297.
Homologues: Orthologues: chimpanzee Metazoa_SRP (98% identical), macaque Metazoa_SRP (90% identical). Paralogues in human: RN7SL1 (78% identical), RN7SL2 (77% identical), RN7SL45P (77% identical), RN7SL3 (77% identical), RN7SL769P (76% identical), RN7SL322P (76% identical), RN7SL220P (75% identical), RN7SL597P (75% identical), RN7SL566P (75% identical), RN7SL664P (75% identical), RN7SL709P (75% identical), RN7SL714P (75% identical), and 701 more.